EGF (epidermal growth factor)
Diseases named in the same sentence as EGF in open-access papers (continued):
Sharing a sentence is not in itself a finding about the gene and the disease.
glioma (continued). "In gliomas, our data showed that EFEMP1 binding to EGFR blocked EGF-mediated activation of PI3K and MAPK signaling pathways, while in pancreatic carcinoma cells it was shown to promote these activities." (PMID 25594013, 2014). "Similar effects were also found in U251 glioma cells, where 20-HETE inhibition by HET0016 reduced an EGF-R activation and, subsequently proliferation stimulated by EGF." (PMID 25549350, 2014). "EGF mediates an increase in KCa1.1 channel activity in vascular smooth muscle cells (VMSC) and controls KCa3.1 channel activation in VMSC and glioma cells." (PMID 25265278, 2014). "In previous reports, GSCs were isolated from glioma tissues as spheres cultured in SFM containing stem-cell mitogens, epidermal growth factor and fibroblast growth factor, which is the same method used to isolate neural stem cells from brain tissue." (PMID 23955054, 2014). "Further, EGF regulated both GSK-3α and 3β, but only pSer9-GSK-3β was enriched at the leading edge of scratched glioma cells." (PMID 24312592, 2013). "Collectively, these data indicated that EGF inhibited GSK-3 mainly through atypical PKC and MAPK pathways, which were important for glioma cell invasion." (PMID 24312592, 2013). "Thepresence in glioma C6 CM of high amounts of HGF, VEGF, zonulin and PGE2, together withthe low abundance of EGF, promoted ReNcells CX transmigration." (PMID 23637756, 2013). "Western blot analysis showed that EGF up-regulate phosphorylated GSK-3α and -3β levels in glioma cells upon mechanically scratching." (PMID 24312592, 2013). "Epidermal growth factor expression and stimulation of its cognate receptor (EGF/EGFR) have emerged as a pivotal signaling mechanism in high grade glioma." (PMID 23737783, 2013). "Microglial cells recruited by glioma can promote tumor growth, dictated by paracrine loops responsible for glioma initiation and progression (e.g., IL-6, IL-10, TGF-β, prostaglandins, G-CSF, and GM-CSF, and growth factors such as EGF, VEGF, HGF, and SCF)." (PMID 22319429, 2012). "EGF/EGFR signalling through extracellular signal-regulated kinases 1/2 (ERK1/2) and casein kinase-2 (CK2) in glioma cells results in the phosphorylation of α-catenin at serine 641, which correlates with glioma malignancy." (PMID 22400111, 2012). "Epidermal growth factor (EGF), a potent mitogenic protein, plays an important role in the development of cancers, including glioma." (PMID 22829952, 2012). "Epidermal growth factor (EGF), which promotes migration of glioma cells, increased the phosphorylation of NKCC1 through a PI3K-dependant mechanism." (PMID 22570591, 2012). "Despite the strong reduction of γH2AX and the generally assumed anti-apoptotic nature of EGF and FGF-2, acute addition of these two cytokines did not reduce but even tended to enhance IR-induced apoptosis of differentiated glioma cells." (PMID 21663643, 2011). "Microscopic analyses showed that in vitro culture of T98G, U87MG, DB29 and DB33 glioma cells in NBM with B27 and EGF+bFGF resulted in the expansion of BTSCs as gliospheres in 5 days." (PMID 21224854, 2011). "GL261 glioma cells form neurospheres when grown in a serum free medium supplemented with FGF and EGF." (PMID 20515450, 2010). "Several growth factors pathways, particularly those downstream of the epidermal growth factor (EGF), platelet-derived growth factor (PDGF) and TGF-β receptor families, have been shown to be activated in gliomas." (PMID 20339555, 2010). "QD-EGF (mono-biotinylated EGF coupled to Streptavidin-(PEG)- QDs, Invitrogen) was applied to cultured human glioma cell-lines in monolayer culture at 37°C." (PMID 20614029, 2010). "Among these factors, IL-6 and EGF consistently promoted Pyk2 activation across all glioma cell lines tested, regardless of their baseline levels of total Pyk2 expression." (PMID 40867240, 2025).
glioma (continued). "In glioma, interleukins, EGF, fibronectin, and HSPG are frequently overexpressed and positively regulate the cell adhesion, proliferation, growth, metastasis, and wound healing processes, thereby contributing to glioma progression and TME remodeling." (PMID 41268299, 2025). "These cells expressed stemness markers, could grow as spheres in a serum-free medium with growth factors EGF and FGF-2 and formed tumors in the brain of immunodeficient mice, reproducing histological features of human gliomas." (PMID 38392188, 2024). "EGF-induced YANK2 phosphorylates p70S6K at T389, activates p70S6K to promote cell proliferation, enhances the tumorigenicity of glioma cells, and significantly reduces the survival time of glioma patients." (PMID 38714727, 2024). "TAMs produce many proteins that can enhance glioma proliferation and/or migration, such as stress-inducible protein 1 (STI1), epidermal growth factor (EGF), colony-stimulating factor 1 (CSF-1), chemokine ligand 2 (CCL2), interleukin-6 (IL-6), and transforming growth factors: TGF-β and -β2." (PMID 39452154, 2024). "Previous studies have reported that GAMs could release factors, such as epidermal growth factor (EGF), and transforming growth factor-β (TGF-β), to increase the migration and growth of glioma cells." (PMID 36969175, 2023). "Research has reported that EGF could induce STAT1 expression to exacerbate the IFN-γ-mediated PD-L1 axis in EGFR-positive cancer cell lines, excluding glioma, and blockade of EGFR by afatinib inhibited EGF- and IFN-γ-mediated PD-L1 expression." (PMID 37759950, 2023). "Moreover, the culturing medium is serum-free and is commonly supplemented with growth factors (EGF and FGF-2), which perpetuates the stem cell phenotypes frequently observed in glioma cells and establishes robust glioma stem cell (GSC) cultures." (PMID 37920169, 2023). "Overall, current studies support an EGF-dependent role of TRPC1 on glioma on migration via chemotactic attraction toward EGF, while basal glioma cellular motility does not seem to be TRCP1 dependent." (PMID 36768856, 2023). "Mutations in isocitrate dehydrogenase (IDH), vascular endothelial growth factor (VEGF), epidermal growth factor (EGF), platelet-derived growth factor (PDGF), and hepatocyte growth factor (HGF) have been recognized to be involved in aberrant proliferation of glioma cells." (PMID 35922753, 2022). "In addition, PRKN inhibits glioma cell growth in vitro and in vivo by downregulating the intracellular levels of β-catenin and EGFR, leading to decreased activation of both Wnt- and EGF-stimulated pathways." (PMID 35832194, 2022). "We obtained glioma stem cells using specific media (DMEM/F12, with 2% B27, 25ng/mL bFGF, 25ng/mL EGF and 1% penicillin/streptomycin) and verified the changes in mRNA levels (CD133 U251 vs. GSCU251: P=0.0005; SOX2 U251 vs. GSCU251P=0.0034) and protein levels of their stem-biological markers." (PMID 36527092, 2022). "A recent study demonstrated that EGF-mediated activation of MMP-9 occurred through increased PI3K/Akt, ERK1/2, and STAT3/STAT5 signalling in glioma cells, leading to NF-κB localisation to the promoter of the MMP-9 gene and promoting GBM migration and invasion in vitro." (PMID 36497413, 2022). "Cell migration studies support the role of microglia-derived PDGFβ, EGF, and SDF1α in Pyk2- and FAK-dependent glioma dispersal: all evaluated cell lines demonstrated enhanced migration under the influence of MCM, as well as PDGFβ or EGF, and this effect was inhibited by Pyk2 and FAK knockdown." (PMID 34944779, 2021). "Besides EGF/EGFR signaling, current findings are consistent with the ROS/ER stress axis likely being a target for the anti-glioma actions of gefitinib." (PMID 33920356, 2021). "The receptors for EGF (EGFR) and PTN (PTPRZ1) have important roles in the genesis of gliomas." (PMID 33925547, 2021).
glioma (continued). "Indeed, treatments with IL-6 and EGF activated Pyk2 and FAK phosphorylation in all evaluated glioma cell lines, while the effect of PDGFβ, SDF-1α, and IL-8 was patient dependent." (PMID 34944779, 2021). "Our studies suggest that stromal-derived factor 1α (SDF-1α), EGF, platelet-derived growth factor β (PDGFβ), and IL-6 are key microglia-derived mediators of Pyk2 and FAK activation in primary human glioma cell lines, leading to increased invasion and proliferation." (PMID 34944779, 2021). "In glioma, exosomes are used as a vehicle to transport EGFRvIII, a mutant epidermal growth factor, to cells that do not have it—inducing the expression of anti-apoptotic genes and increasing the anchorage-independent growth capacity." (PMID 34576294, 2021). "In response to these signals, GAMs release multiple cytokines such as transforming growth factor ß (TGF-β), stress-inducible protein 1 (STI-1), prostaglandin E2 (PGE2), IL-6, IL-1β, IL-10, and epidermal growth factor (EGF), which promote glioma cell proliferation and inhibit T cells function." (PMID 34084145, 2021). "Indeed, the role of microglia in glioma invasiveness has also been related to the secretion of SIP1, EGF and TGF-β." (PMID 33802571, 2021). "Therefore, the findings reported in this study demonstrate that PDGFβ, EGF, and SDF-1α are the main effectors of glioma cell migration through Pyk2 and FAK activation." (PMID 34944779, 2021). "Several factors that are synthesized and released by microglia/TAMs have been reported to increase the invasion of glioblastomas or glioma, such as stress-inducible protein 1 (STI1), epidermal growth factor (EGF), IL-6, and MT1-MMP (membrane type 1-matrix metalloproteinase)." (PMID 33330047, 2020). "Interestingly, when stimulated with epidermal growth factor (EGF), TRPC1 relocated to the leading edge of migratory glioma cells (D54MG), suggesting a growth factor mediated role for TRPC1 in the migration of cancer cells." (PMID 33096667, 2020). "Interestingly, the co-upregulation of Rab27b and epiregulin (EREG), a member of the epidermal growth factor (EGF) family, correlated with radioresistance in glioma cell lines." (PMID 33409495, 2020). "However, TAMs secrete a wide array of cytokines, including epidermal growth factor and TGF‐β, to promote glioma migration and invasion." (PMID 32969157, 2020). "We found that the expression of STAT5b, a transcription factor that could be phosphorylated in EGF or HGF dependent manner and promoted the malignant progression of gliomas 29, 43, was abnormally upregulated in TMZ resistant cells." (PMID 32194873, 2020). "In aggressive glioma cells, TRPC1 regulates epidermal growth factor (EGF)-evoked migration." (PMID 32138386, 2020). "Similarly to EGF, platelet-derived growth factor (PDGF) also activates proliferation of NSCs in the SVZ and creates areas of hyperplasia with features of early glioma formation." (PMID 31482066, 2019). "Also, gliomas induce the overexpression of other mitogens, including IGF-1 (Insulin like Growth factor) and EGF (Epidermal growth factor) as well." (PMID 31799246, 2019). "The glioma cell lines were cultured both in standard culture medium (DMEM supplemented with FBS 10% - “St-M”) and in culture medium for GSC generation (DMEM/F12 medium serum free with EGF, b-FGF and B27 supplement - “GSC-M”)." (PMID 28424427, 2017). "Moreover, normal NSCs express EGFR and therefore, it seemed only natural to keep glioma cells in NSC media in vitro, which has EGF and FGF-2 as the main growth factors." (PMID 28978189, 2017). "Another factor, known to stimulate both proliferation and migration, is the epidermal growth factor (EGF); indeed, overexpression of its receptor (EGFR) is a feature which characterizes high-grade gliomas, with the highest expression level at the invasive niche." (PMID 29261132, 2017).
glioma (continued). "After a few passages of the glioma tissue obtained from a 64-year-old wild-type IDH1 GBM patient, cells were mechanically dissociated into single cells and then placed individually in uncoated 96-well plates and cultured in the presence of EGF and FGF." (PMID 25623281, 2015). "Under NSCM with bFGF and EGF, N2 and without serum, GSCs were obtained from human glioma primary cultures or glioma cell lines, maintained parental tumor molecular phenotype, and even kept parental genotype." (PMID 25879429, 2015). "Taken together, these results suggest thatthe absence of EGF in glioma C6 CM favors a leaky state of the BBB that helps the transmigration orReNcells CX." (PMID 23637756, 2013). "When glioma cells stimulated with serum or EGF, GSK-3β was regulated through its localized inhibition, characterized by the increased phosphorylation at the Ser9 of GSK-3β (pSer9-GSK-3β) at the leading edge of migrating glioma cells." (PMID 24312592, 2013). "EGF and FGF are growth factors that promote the tumourigenicity of glioma cells." (PMID 21224854, 2011). "These include epidermal growth factor (EGF), platelet-derived growth factor (PDGF), insulin-like growth factor 1 (IGF-1), and their specific receptors (EGFR, PDGFR, and IGFR), all of which are involved in autocrine or paracrine signaling in gliomas." (PMID 22091432, 2011). "For instance, EGF and PDGFB were clustered together and they are both involved in several pathways: cytokine-cytokine receptor interaction, MAPK signaling pathway, gap junction, focal adhesion, glioma and regulation of actin cytoskeleton." (PMID 21726470, 2011). "For example, epidermal growth factor (EGF) could be used to specifically target EGF receptor- (EGFR-) positive tumours (these include melanomas, gliomas, breast, prostate, and ovarian cancers)." (PMID 20871837, 2010). "As an important receptor of EGF with high affinity, EGFR was often overexpressed in glioma cells." (PMID 20487573, 2010). "These previous studies suggested that overexpression of EGF and EGFR might affect cell activities in brain tissues, abnormity of which may contribute to the glioma." (PMID 20487573, 2010). "Similarly, in vitro treatment of T98G glioma cells with ciglitazone (f), 15d-PGJ2 (j) or ATRA (n) cultured in NBM+B27 with EGF+FGF resulted in 44, 65 and 78% inhibition of proliferation, respectively." (PMID 19018263, 2008). "Moreover, in vitro treatment of U87MG glioma cells with ciglitazone (e), 15d-PGJ2 (i) or ATRA (m) cultured in NBM+B27 with EGF+FGF resulted in 46, 72.26 and 81% inhibition of proliferation, respectively." (PMID 19018263, 2008). "In contrast, glioma cell lines with high Pyk2 expression may rely on additional or alternative signaling pathways beyond Pyk2 and FAK for migration in response to SDF-1α and EGF, although Pyk2 still appears to act as a central regulator of cell dispersal." (PMID 40867240, 2025). "For instance, in glioblastoma, circular E-cadherin RNA (circ-E-Cad) produces a secretory E-cadherin protein variant through multiple-round open reading frame (ORF) translation, activating EGFR signaling independent of EGF and maintaining glioma stem cell tumorigenicity." (PMID 38802795, 2024). "Furthermore, miR-374a-targeted genes exhibited significant association with pathways such as cancer, Ras signaling, MAPK signaling, PI3K-AKT signaling, Glioblastoma signaling, EGFR tyrosine kinase inhibitor resistance, mTOR signaling, miRs in cardiomyocyte hypertrophy, EGF/EGFR signaling and glioma." (PMID 39348350, 2024). "Notable pathways included MAPK signaling, cancer pathways, EGF/EGFR signaling, Glioblastoma signaling, Ras signaling, EGFR tyrosine kinase inhibitor resistance, miRs in cancer, PI3K-AKT signaling, p38 MAPK signaling, glioma, miRs in cardiomyocyte hypertrophy, and mTOR signaling." (PMID 39348350, 2024). "In addition, we sorted CD133-CD15- glioma cells three times and cultured cells under hypoxic conditions without EGF and FGF2." (PMID 34976166, 2022).
glioma (continued). "Additionally, the evaluated glioma cell lines showed increases in total Pyk2 and FAK protein expression upon treatment with SDF-1α, IL-6, and EGF, indicating regulation of Pyk2 and FAK signaling at the level of protein synthesis, in addition to the regulation of phosphorylation." (PMID 34944779, 2021). "In addition, approximately 60% of all gliomas have an amplified gene coding epidermal growth factor receptor (EGFR), which, by binding to epidermal growth factor (EGF), contributes to its increased activity and promotes proliferation and intracellular signaling disorders." (PMID 32977537, 2020). "EGF signaling through the EGF receptor is essential for not only the proliferation of neural stem cells (NSCs) but also the proliferation of glioma stem cells." (PMID 32102678, 2020). "Because Src is involved in the signaling pathway evoked by EGF and FGF-2, and TAT-Cx43266–283 reduces Src activity in astrocytes and in glioma stem cells in vitro and in vivo, we aimed to confirm whether Src activity is also inhibited by TAT-Cx43266–283 in PC NPCs." (PMID 33238452, 2020). "Many of the soluble factors involved in GAM-glioma crosstalk have been identified, such as epidermal growth factor (EGF), which is released by MG and stimulates GBM cell migration and invasion via the commonly upregulated epidermal growth factor receptor (EGFR) on glioma cells." (PMID 33117364, 2020). "ErbB and its ligand epidermal growth factor (EGF) are reported to participate in both glioma development and schizophrenia neuropathology, so antipsychotic drug targeting the EGF/ErbBs signaling pathway can affect the tumorigenesis of glioma in persons with schizophrenia." (PMID 30233327, 2018). "More recently, the Uhrbom lab has established a biobank of glioma cell lines (The Human Glioblastoma Cell Culture Resource) with over sixty cell lines from surgical GBM samples, by growing them first as spheres and then as monolayer cultures in EGF/FGF-2 enriched media." (PMID 28978189, 2017). "However, under the absence of EGF in glioma C6 CM, thepresence of PGE2 could exert a deleterious effect on the TEER." (PMID 23637756, 2013). "Notably, MAP4K4 expression is upregulated by EGFRvIII expression in glioma cells, and it is known to interact with the FERM domain of classical ERM proteins and phosphorylates them to promote F-actin anchoring and stabilization of lamellipodia in response to EGF and PDGF." (PMID 24163766, 2013). "EGF is considered a promoter of GAM-mediated tumor invasiveness, as it is not detectable in the supernatant or cell lysate of glioma cells cultured separately." (PMID 36969167, 2023). "We tested supplementing with epidermal growth factor (EGF) and fibroblast growth factor-2 (FGF-2b), two growth factors used for glioma stem cell maintenance, as well as N2 and B27 without vitamin A, two supplements optimized for neural cell culture." (PMID 35906273, 2022). "T4 at physiological free concentrations also was found nongenomically to potentiate induction by epidermal growth factor (EGF) of c-Fos expression, and c-Fos has subsequently been found to promote cancer cell radioresistance in glioma cells." (PMID 30651936, 2018). "This agrees with our findings that the global transcriptomic profiles between RMPAhigh gliomas with or without EGFR alteration were highly similar, and that EGFR ligand AREG and EGF were enriched in the RMPAhigh gliomas." (PMID 27385209, 2016). "Epidermal growth factor (EGF) is capable of stimulating NSC migration, although it has beenreported that it is not produced in any significant quantity by gliomas." (PMID 23637756, 2013). "With nanoinhibitors as treatments on TMZ-resistant glioma cells, BIP-MPC-NP simultaneously attenuated p-EGFR and p-MET in cells with EGF and HGF incubation or without EGF and HGF incubation, and this attenuation was more significant than that of EBP-MPC-NP or MBP-MPC-NP group." (PMID 32001707, 2020).
glioma (continued). "Moreover, the up-regulation of CD133 may be influenced by EGF and FGF2 in stem cell medium, so what's the influence of hypoxia microenvironment on differentiated glioma cells is not clear." (PMID 28427209, 2017).